RN7SKP255 (RN7SK pseudogene 255)
Gene: Miscellaneous RNA gene on chromosome 14 (89,712,511 to 89,712,823, forward strand). Ensembl gene ENSG00000200312.
Homologues: Paralogues in human: RN7SKP203 (81% identical), RN7SKP176 (80% identical), 7SK (80% identical), RN7SKP71 (80% identical), RN7SKP79 (79% identical), RN7SKP180 (79% identical), RN7SKP9 (79% identical), RN7SKP281 (78% identical), RN7SKP204 (77% identical), RN7SKP90 (77% identical), RN7SKP224 (77% identical), RN7SKP124 (76% identical), and 284 more.
Diseases named in the same sentence as RN7SKP255 in open-access papers:
RN7SKP255 is named in the same sentence as 4 diseases in open-access papers, as found by Europe PMC text mining. Sharing a sentence is not in itself a finding about the gene and the disease. The quoted sentences say what the papers report.
lung adenocarcinoma (1 paper, 2025). A carcinoma that arises from the lung and is characterized by the presence of malignant glandular epithelial cells. "The RN7SKP255 gene was found to be upregulated in lung adenocarcinoma compared with adjacent non‐tumorous tissue while RN7SKP80 plays a contributing factor in distinguishing pancreatic cancer from normal tissue." (PMID 40788820, 2025).
RN7SKP255 also shares sentences with these, for which no sentence is quoted: cancer (1 paper); leukemia (1); pancreatic cancer (1).